IL7 (interleukin 7)
Diseases named in the same sentence as IL7 in open-access papers (continued):
Sharing a sentence is not in itself a finding about the gene and the disease.
infection (continued). "Dam 3 exhibited an increase above baseline in IL-2, IL-6, IL-7, and IL-15; notably, all cytokines increased on day 7 and returned to basal by day 14 post-infection." (PMID 30657788, 2019). "Although circulating IL-7 levels rise, IL-7 bioavailability in the lymphoid tissues is significantly decreased following infection due to TGF-β1-mediated collagen deposition that results in the loss of IL-7-producing fibroblast reticular cell (FRC) networks." (PMID 31507594, 2019). "Concomitant with the stromal breakdown after 14 days post infection, Il3, Gm-csf, and Scf expressions were significantly diminished on day 14 pi, followed by a decrease of Il7 gene expression on day 21 pi, but the factors were restored later during infection." (PMID 30619242, 2018). "During the acute phase of infection, various pro-inflammatory innate immune factors become active, such as interleukin (IL)-6, IL-7, IL-8, IL-12p70, IL-15, IP-10, and MCP-1." (PMID 30254258, 2018). "Consistent with previous study, here we showed that the expression of IL‐7 significantly increased after transcutaneous infection of mice with schistosome cercariae, correlating with the enhancement of the immunopathology in the liver." (PMID 29566311, 2018). "IL-2 and IL-9 are involved in cell proliferation and are also present at high levels during the convalescent phase, whereas IL-7 and IL-13 remain elevated until 3 months post infection." (PMID 30254258, 2018). "Exhausted virus-specific T cells also become less responsive to the critical γc survival cytokines IL-2, IL-7, and IL-15 (10, –, 12), although exogenous IL-2 and IL-7 can be used therapeutically to promote virus control in an established LCMV Cl13 infection." (PMID 29593047, 2018). "To examine the association of circulating common γ-chain cytokines with TB disease or infection, we examined the systemic levels of IL-2, IL-7, IL-15, and IL-21 in individuals with PTB, latent TB (LTB) or no TB infection (NTB)." (PMID 28448542, 2017). "There was a T allele dependency on IL-7, IL-8, IL-17, and CCL5 serum level in the patients during the acute phase of the infection." (PMID 28512644, 2017). "Interleukin gene activation was limited to IL1A, IL1B, IL7, and IL15 at 6 h, followed by a downregulated expression of all genes, except IL7, at 16 h of infection." (PMID 28993767, 2017). "This revealed 13 mediators of inflammation that correlated with infection status, which were, in order of strength of significance, IL-4, IL-5, IL-7, IL-15, IFN-α, IL-12, IFN-γ, IL-17, IL-1Ra, TNF-α, IL-1β, IL-10, and IL-2." (PMID 27418744, 2016). "IL-7 is involved in early T cell development and IL-6 is a pro-inflammatory cytokine involved in stimulating an immune response during infection." (PMID 27472318, 2016). "We further show that reduced levels of type I interferon and IL-7 and elevated levels of IL-6, IL-8, IL-10 and VEGF strongly associated with severe disease both in primary and secondary infections." (PMID 26982706, 2016). "Latently infected T-cells were prepared by infection of naïve CD4+ T-cells with HIV-1 NL4-3 followed by culture with IL-7/TGFβ-1 for 2 weeks, a condition modified based upon previous publications." (PMID 27049645, 2016). "For example, a random expression cDNA library can be produced from the high IL-7-expressing cells, and then introduced into the IL-7 reporter cells by infection." (PMID 27589392, 2016). "Treating resting CD4+ T cells with CCL19 increased productive infection 2-fold over untreated cells, while IL-7 treatment produced a 5-fold increase in productive infection." (PMID 26067822, 2015). "These cells were either left untreated or were treated with the cytokine IL-7 or the chemokine CCL19 for 72 h prior to infection." (PMID 26067822, 2015). "Another study showed that septic mice treated with recombinant IL-7 (rhIL-7) increase the local and systemic production of neutrophils and IL-17, thus recruiting more neutrophils to the site of infection." (PMID 25614712, 2014).
infection (continued). "In HIV-1BaL-infected cervico-vaginal tissues IL-7 25 ng/mL increased Bcl-2 expression in uninfected CD4+ T cells on average 2.0±0.3 fold on day 9 post infection (n = 4, p<0.05)." (PMID 23408885, 2013). "In lymphoid tissues pre-treated overnight with IL-7 and cultured in the presence of IL-7 until day 3 post infection, HIV-1LAI.04 replication was increased 6.3±1.4 fold (n = 4, p<0.01)." (PMID 23408885, 2013). "On average, IL-7 25 ng/mL increased the fractions of HIV-1-infected CD4+ (CD8− p24gag+) T cells 3.0±0.9 fold on day 9 post infection (n = 5, p<0.05)." (PMID 23408885, 2013). "In these experiments, we included IL-7 (10 ng/mL) in all cultures to increase cell survival of the resting cells and infections were performed at an MOI of 5 to ensure a high frequency of latently infected cells." (PMID 24339779, 2013). "IL-7 25 ng/mL increased Bcl-2 expression in HIV-1-infected CD4+ T cells on average 1.5±0.1 fold on day 9 post infection, compared with donor-matched infected untreated tissues (n = 4, p<0.05)." (PMID 23408885, 2013). "We used a macaque model to show that treatment with IL-7 has beneficial effects if implemented during the acute phase of infection with SIV, the simian AIDS virus." (PMID 22511868, 2012). "Increased plasma levels of IL-7, albeit considerably lower than in IL-7-treated animals, were also observed in untreated animals starting on day 28 post-infection in parallel with the most pronounced reductions in circulating lymphocyte counts." (PMID 22511868, 2012). "IL-7-treated animals experienced sustained increases in all subsets of circulating CD8+ T cells throughout the acute phase of infection, whereas a transient decline of naïve and memory CD8+ T cells was observed in untreated animals." (PMID 22511868, 2012). "Consistent with what was seen with the effect on STAT-5 activation, infection with HIVcs204 inhibited the ability of IL-7 to induce Bcl-2 expression in thymocytes." (PMID 21920046, 2011). "While 20% and 50% mortality was noted in control KO mice and anti IL-7 treated WT mice respectively, all the animals treated with anti IL-7 antibody succumbed to infection by day 26 p.i.." (PMID 20520779, 2010). "One day prior to infection WT and KO animals were administered anti IL-7 antibody or equal volume of saline via i.p. route." (PMID 20520779, 2010). "Anti IL-7 treatment of KO mice severely reduced their ability to clear infection as maximal parasite burden was observed in the tissues of these animals." (PMID 20520779, 2010). "Previous studies from our laboratory have reported that exogenous treatment of infected mice with IL-7 augments CD8+ T cell response against T. gondii resulting in their ability to survive lethal infection." (PMID 20520779, 2010). "While resting T cells are normally refractory to productive infection by lentiviruses and lentivirus-derived vectors, a sizable fraction becomes permissive for infection when cultured in the presence of cytokines such as IL-7." (PMID 14737186, 2004). "The elevated levels of IP-10, RANTES, and IL-1RA, together with reduced IL-7, may reflect heightened antiviral signaling and immune cell recruitment during infection." (PMID 41552277, 2025). "Thirteen of the tested proteins (G-CSF, GM-CSF, M-CSF, TNF-β, IFN-gamma, TNF-α, IL-1 β, IL-3, IL-6, IL-7, IL-15, IL-17, IL-19) were found in the hemolymph and hemocytes of G. mellonella; however, the results regarding the influence of infection differed according to the detection method." (PMID 38774871, 2024). "Here, our finding demonstrated the abnormal level of certain cytokines in convalescent COVID‐19 patients, indicating residual long‐term effect of the infection., and reduced IL‐7 level may correlate with diminished T cell number and function." (PMID 36938980, 2023). "In addition, after recovery from the infection, both groups of patients presented elevated levels of IL-7, a pleiotropic cytokine essential for lymphocyte survival and expansion." (PMID 36975498, 2023).
infection (continued). "In addition, aged ferrets showed high expression of chemokines (CCL4 and CXCL10) and inflammatory cytokines (IFNB1, IL1B, IL6, and IL7) in the early phase of infection." (PMID 35013229, 2022). "The number of IL-7-eGFP+ stromal cells also significantly increased during infection." (PMID 34997007, 2022). "IL-7 is currently in clinical trials for treatment of infections and tumors." (PMID 34997007, 2022). "Additionally, there was a strong trend to increased IL-10 (anti-inflammatory) shortly after infection, and a significant increase in IL-7 (drives lymphocyte development) late in infection." (PMID 33376758, 2021). "ITAC, Fractalkine, IL-7, IL-8, and TNFα were identified as markers predictive for pre-infection." (PMID 33731158, 2021). "IL-7 is also a cytokine that indicates the acute phase of infection induced liver inflammation." (PMID 35054427, 2021). "The KEGG pathway enrichment analysis demonstrated that the top pathways involved in TNF signaling, NOD-like receptor signaling, IL-7 signaling, and cytokine-cytokine receptor signaling pathways were overrepresented in the upregulated genes after 6 h of infection." (PMID 33585271, 2020). "Dam 4 exhibited an increase above baseline in IL-1β, IL-2, IL-6, IL-7, IL-15 and IL-16, and similar to Dam 2, peak levels of these cytokines were on day 14 post-infection with the exception of IL-15 (day 7); by 21 dpi, most cytokines had returned to baseline or were lower than peak levels." (PMID 30657788, 2019). "On the other hand, IL-7 was depressed during early infection in both UC1 and UC2 groups." (PMID 31614626, 2019). "In order to investigate whether intestinal IL-7 production could be initiated by local infection, we quantified SIV DNA and RNA in tissues from SIV-infected monkeys." (PMID 28579989, 2017). "We here assessed IL-7 expression and comprehensively studied chemokine networks and immune cell subsets in the gastrointestinal tract of Chinese rhesus macaques during acute SIVmac251 infection, with a particular focus on CD4+ macrophages and T-cells." (PMID 28579989, 2017). "Maximal IL-7 transcription was observed at day 7–10 post-infection (pi) (p = 0.009)." (PMID 28579989, 2017). "Altogether, our observations are consistent with IL-7 being an infection-induced early danger signal that may participate in driving the massive changes that occur within the small intestine chemokine network in response to infection." (PMID 28579989, 2017). "IL-7 or IL-15 may also contribute to a qualitatively or quantitatively different cytokine milieu during the infection with M. tuberculosis, and signaling by both IL-7 and IL-15 synergizes to promote the generation of memory T cells responses." (PMID 28448542, 2017). "As LCMV has been shown to infect BM stromal fibroblast and endothelial cells, it could well be that the cellular sources of IL-7 and IL-15 in the BM are severely affected by the infection." (PMID 26793197, 2015). "Latent infection increased by 3-fold after treatment with either CCL19 or IL-7." (PMID 26067822, 2015). "In fact, we found the frequency and absolute numbers of viral-specific CD8+ T cells were significantly higher in the GIFT7-treated group, even compared with young animals, at day 21 post infection when the level of PBS- or GMCSF+IL7-treated groups was barely detectable." (PMID 26131365, 2015). "IL-7 promotes survival and differentiation of memory CD8 T-cells, suggesting that increased IL-7 production during LN remodeling in the resolution phase of an infection could potentially play a role in enhancing T-cell memory." (PMID 25580369, 2014). "Despite the nearly complete depletion of developing B cells during early infection, the frequencies of naïve, germinal center and memory B cells harboring viral genome in the anti-IL-7 treatment group were nearly identical to that of mock and isotype control groups." (PMID 24516386, 2014).
infection (continued). "Similarly, administration of IL-7 in chronic LCMV infection model overcame infection and limited organ damage." (PMID 24603698, 2014). "Similarly, IL-7 enhanced HIV-1 replication when infection was performed on the background of human seminal fluid." (PMID 23408885, 2013). "High levels of seminal IL-7 in vivo may be relevant to the survival of the founder pool of HIV-1-infected cells in the cervico-vaginal mucosa at the initial stage of infection, promoting local expansion and dissemination of HIV infection." (PMID 23408885, 2013). "However, there was a trend towards higher levels of viremia in IL-7-treated animals, particularly on days 35 and 41 post-infection, even though the statistical p values remained far below the threshold for significance." (PMID 22511868, 2012). "The depletion of FRCs correlates with a parallel increase in collagen deposited outside the FRC network, so that as infection progresses, fewer and fewer T cells are in contact with and have access to IL-7 on the FRC network compared with uninfected populations." (PMID 22241988, 2012). "However, the protective effects of IL-7 were not sustained after treatment interruption with both naïve and memory CD4+ T cells becoming significantly decreased, compared to baseline values, on day 62 post-infection, 4 weeks after the last injection of IL-7." (PMID 22511868, 2012). "Pro-inflammatory cytokines such as IL-1β, IL-4, IL-6 and IL-7 participate in this infection." (PMID 17935610, 2007). "IL-1β was found only after 10 and 20 h of infection, and IL-7 level was elevated only after 5 h." (PMID 16834785, 2006). "Integrating IL-7 into current ART regimens might improve immune recovery and reduce infection risk." (PMID 41327829, 2025). "Although further study is required, it is tempting to speculate that elevated IL-7 levels in infancy or later childhood may have contributed to the relatively high frequencies of both infection and clonal expansion reported for naive CD4+ T cells of participant 1001." (PMID 40048262, 2025). "Additionally, interleukin-7 (IL-7) was upregulated by LASV LF2384 infection in contrast to LF2350." (PMID 38826374, 2024). "We speculate that this early effect of IL-7 to direct lymphocytes to areas of infection is inherently beneficial by helping to contain and eliminate the microbial pathogens, but may be excessive when IL-7 plasma concentrations are dramatically (100-fold) elevated when administered intravenously." (PMID 36906875, 2023). "Interestingly, levels of pro-inflammatory cytokines reduced as time passed from the beginning of infection, while IL-7 and IFN-γ and IL-10 tended to increase, showing the recovery of a more functional immune system and of mechanisms to counterbalance inflammation." (PMID 36675231, 2023). "Interestingly, the majority of IL-7-eGFP+ cells during infection are epithelial cells." (PMID 34997007, 2022). "However, IL-7-eGFP+ lymphatic endothelial cells were reduced following infection." (PMID 34997007, 2022). "Taking into account the biological activity of IL-7, we made an attempt to examine its association with immune function assessed in terms of lymphocyte count, lymphocyte-to-neutrophil ratio, and the dynamics of Th1 cytokine interferon (IFN)-γ as well as the occurrence of surgical site infections." (PMID 29904108, 2018). "Similarly, IL-7R internalization triggered by IL-7 stimulation may explain the reduced CD127 expression characterizing circulating HIV-specific CTLs during hyperacute infection in patients." (PMID 28579989, 2017). "However, IL-15 SA predominantly expands NK, NKT, and mCD8+ lymphocytes, whereas preferential expansion of naïve and effector CD4 and CD8 T-lymphocyte populations, with therapies such as IL-7, may provide more effective resistance to infection." (PMID 26859674, 2016).
infection (continued). "Because survival of naïve T cells is dependent on access to IL-7, the collagen deposition-restricted access to and loss of the FRC network itself should result in an increase in apoptosis proportional to the extent of collagen deposition and decreased IL-7 source as infection progresses." (PMID 22241988, 2012). "On the other hand, pro-inflammatory cytokines IL-1β, IL-7, IL-18, and chemokines MCP-1 and MIP-1α were upregulated after infection with rCDC-9 P11 compared to rCDC-9 P45." (PMID 41060027, 2025). "Our analysis revealed differential expression patterns for several immunological genes, including CD94, CD19–2, CD23, IL-7, and CIITA, during LF2384 and LF2350 infection." (PMID 38826374, 2024). "Two-way ANOVAs revealed significant interactions between EcoHIV infection and B/F/TAF treatment for IFNγ, IL-7, IL-10, and RANTES." (PMID 38786105, 2024). "In the case of SARS-CoV-2, an increase in the concentration of inflammatory cytokines such as IL-1β, IL-2, IL-6, IL-7 and TNF-α comes to the fore, along with the rise in IL-4 and IL-10 concentrations in a later stage of infection." (PMID 36294388, 2022). "In Rwanda, Fractalkine, GMCSF, ITAC, IL-1ß, IL-6, IL-7, IL-8, MIP-1α, and TNFα concentrations were significantly increased in the pre-infection group compared to the uninfected group." (PMID 33731158, 2021). "IL-7 can also be increased in HIV-1 and SIVmac infection as a consequence of CD4+ T cell depletion, as shown during primary infection in the blood and intestine." (PMID 34220857, 2021). "The PLS showed that the levels of GMCSF, Fractalkine, IFNg, ITAC, IL-1ß, IL-2, IL-5, IL-7, IL-8, IL-10, IL-12, IL-17α, IL-21, IL-23, MIP-1ß, and TNFα had higher impact on the separation between the uninfected and the pre-infection cohort." (PMID 33731158, 2021). "Among serum molecules identified in non-neurological and neurological diseases in the acute phase of the infection, 12 (IL-1β, IL-6, TNF, IL-2, IL-7, IL-17A, IL-15, IFN-α, IL-5, IL-13, IL10, and GM-CSF) were shared by both networks." (PMID 33776990, 2021). "In hepatitis C virus (HCV) mono-infection and HIV–HCV co-infection, IL-7 enhances NK-cell degranulation and promotes NK-cell cytolysis of target cells." (PMID 34925323, 2021). "In this article, we will review recent studies of the role of IL-7 and TSLP in ILC development and function during infection and inflammation." (PMID 31921158, 2019). "A recent one-year longitudinal study of confirmed MAYV-infected individuals in Peru found that infection elicited robust anti-viral immune responses including strong neutralizing antibody responses and secretion of pro-inflammatory immune cytokines including IL-13, IL-7, and VEGF." (PMID 30730897, 2019). "Cytokines that are upregulated during acute human infection include IL-6, IL-16, IL-17, IP-10, MCP-1, MIF, stromal cell-derived factor-1α, IL-1rα, IL-2rα, G-CSF, GM-CSF, VEGF, IL-7, IL-12p40, and IFN-α2." (PMID 31053842, 2019). "With restoration of absolute CD4+ T cell levels, IL-7 in the serum decreases and IL-7 mediated STAT-5 phosphorylation, which is elevated in memory CD4+ T cells in untreated infection, is normalized." (PMID 31507594, 2019). "At T1, 2 months post-infection, the LM17- and LJL143-immunized dogs presented higher levels of IFN-γ, IL-6, IL-18, CXCL10, GM-CSF, IL-7, IL-15, and CCL2 in comparison to controls." (PMID 30519235, 2018). "In contrast, recruitment of EBNA2 to host genes IL7 and HES1 was more efficient after the LPKOw infection, consistently showing elevated EBNA2 binding on days 2 and 5, but not at later time points." (PMID 29462212, 2018). "At 4 months after infection (T2), the dogs immunized with either salivary protein presented higher levels of IFN-γ, IL-6, IL-18, GM-CSF, IL-7, IL-15, TNF, and CCL2 when compared to controls." (PMID 30519235, 2018). "RBPJ binding was slightly (but consistently) lower in LPKOw at day 5 post infection at the LMP promoters but identical at Cp and host locus IL7." (PMID 29462212, 2018).